HMGB2 (high mobility group box 2)
Diseases named in the same sentence as HMGB2 in open-access papers (continued):
Sharing a sentence is not in itself a finding about the gene and the disease.
tumor (continued). "HMGB1 and HMGB2 proteins are currently under investigation due to their involvement in DNA replication, transcription, recombination, repair, inflammation, tumor development, and cell signaling." (PMID 33076532, 2020). "Previous studies have shown that HMGB2 and CMPK1 are abundantly up-regulated in various malignant tumors, and are closely associated with tumor development and poor prognosis." (PMID 30699189, 2019). "HMGB2 overexpression was detected at both mRNA and protein levels in tumor tissues from HCC patients." (PMID 31695969, 2019). "Higher HMGB2 expression correlated with larger tumor size (P = 0.003) and advanced tumor stage (P = 0.033)." (PMID 29463261, 2018). "Tumours expressing low levels of SET, but high levels of NM23, or, alternatively, low levels of APE1, but high levels of HMGB2, have a better prognosis compared to other tumours." (PMID 26682011, 2016). "High mobility group box 1 (HMGB1) and HMGB2 overexpression has been observed in several human tumor types, and is involved in cancer progression and prognosis." (PMID 23426143, 2013). "Our study found that HMGB1 and HMGB2 were overexpressed in BCa tissues compared with normal tissues, and were correlated with both the clinical stage and pathological grade of the tumor." (PMID 23426143, 2013). "HMGB2 knockdown disrupts this metabolic shift, reducing lactate production and tumor growth." (PMID 40396172, 2025). "The functional role of HMGB2 in tumor cell behavior was validated through in vitro assays." (PMID 40396172, 2025). "In summary, Hmgb2-deficient CD8+ T cells reverse T cell exhaustion and reduce tumor burden in HCC." (PMID 40315321, 2025). "This section provides insights that HMGB2 influences tumor TME in addition to tumor proliferation." (PMID 40315321, 2025). "In vivo studies will provide insights into how HMGB2 influences tumor growth and spread." (PMID 40396172, 2025). "Given the pivotal role of the PI3K/AKT signaling pathway in NK cell activation and cytotoxicity, we hypothesize that HMGB2 may modulate NK cell anti-tumor function via this signaling axis." (PMID 41280896, 2025). "S4, G and H), suggesting that HMGB2-induced T cell exhaustion phenotypes might rely on constant tumor antigen stimulation." (PMID 40315321, 2025). "Additionally, HMGB2 modulates AMPK signaling to maintain energy balance under metabolic stress and is linked to mitochondrial function, enabling tumor adaptation to hypoxia." (PMID 40396172, 2025). "Additionally, cytotoxicity assays against ESCC cell lines demonstrated that HMGB2 overexpression significantly impaired NK cell-mediated tumor cell killing, with reduced tumor cell lysis observed at multiple effector-to-target ratios." (PMID 41280896, 2025). "Furthermore, when HMGB2 knockdown was combined with Palbociclib treatment, a significant decrease in tumor cell proliferation was observed across multiple cancer models." (PMID 40396172, 2025). "HMGB2 promotes endocrine therapy resistance in tumor cells by regulating DDX18 expression." (PMID 41354099, 2025). "Moreover, HMGB2 expression was consistently elevated in tumor tissues compared to normal tissues across multiple independent cohorts." (PMID 39247201, 2024). "Through an integrated approach encompassing multi-omics analyses, we discovered and validated the pivotal role of HMGB2 in tumor metastasis and the immunosuppressive microenvironment of HCC, highlighting its potential as a therapeutic target and prognostic marker for HCC management." (PMID 39247201, 2024). "GSEA revealed a positive correlation between HMGB2 expression and critical biological processes such as cell cycle regulation, DNA replication, and sister chromatid segregation, suggesting its potential involvement in tumor progression and prognosis." (PMID 39247201, 2024). "The change in HMGB2 subcellular expression in tumor cells from the bulk of the tumor, compared to the infiltrative border, remains to be elucidated and may be related to changes in HMGB2 function." (PMID 38672598, 2024).
tumor (continued). "Targeting HMGB2 may disrupt these critical pathways involved in the metabolic reprogramming of cancer cells, thereby inhibiting tumor growth and progression, offering a promising avenue for improving patient outcomes." (PMID 39247201, 2024). "The numbers of Hmgb2−/− P14 T cells were also significantly decreased in the tumor and TdLNs." (PMID 37704621, 2023). "EEF1AKMT3, BHLHE40, and HMGB2 were activated in 11 tumor-related clusters of P128T." (PMID 37985711, 2023). "Since persistent antigen presentation in tumors also drives differentiation of exhausted CD8+ T cells, we next asked whether HMGB2 regulated tumor-specific CD8+ T cells." (PMID 37704621, 2023). "HMGB2 enhances tumor cell proliferation through the AKT signaling pathway." (PMID 37176041, 2023). "However, previous studies have elaborated on the elevated expression of HMGB2 in several types of tumor tissues and reported it as an oncogene." (PMID 35962344, 2022). "Further tumor xenograft experiments in nude mice also demonstrated that circ_UBAP2 knockdown could increase the expression of miR-637, but decrease the HMGB2 expression, thus promoting OS progression in vivo." (PMID 35114890, 2022). "The molecular reason for these differences in association with tumor stage of HMGB2 vs. HMGB1/3 is not yet understood." (PMID 35923467, 2022). "Besides, over-expression of HMGB2 promoted A549 cells proliferation and migration while knocking down of HMGB2 suppressed the tumor promoting effect." (PMID 35962344, 2022). "Additionally, we found that miR‐524‐5p was down‐regulated and HMGB2 was up‐regulated in NSCLC tumour tissues." (PMID 34651416, 2021). "Furthermore, the tumor formation experiment in nude mice further confirmed that KTN1-AS1 promoted the growth of PC by targeting miR-23b-3p/HMGB2 axis." (PMID 34461605, 2021). "Furthermore, we analyzed in vitro the effects of HMGB2 knockdown on cell growth and on the Warburg effect, which is thought to be fundamental to tumor growth and progress." (PMID 29463261, 2018). "Tumor suppressive miRNAs mediate the degradation or post-transcriptional inhibition of transcripts encoding oncogenes and can target ZEB1/2, HMGB2, Bcl2 and HIF-1α, which contribute to the increased proliferation, invasion, and EMT and reduce the apoptosis of cancer cells." (PMID 28085956, 2017). "However, many of the results demonstrating HMGB2 overexpression were based on measurements derived from tumor tissue, and far less is known about the implications of dysregulated HMGB2 expression in peripheral blood leukocytes and its role in cancer risk." (PMID 24479488, 2014). "In the present study, immunohistochemistry and real-time polymerase chain reaction (PCR) of HMGB1 and HMGB2 in 64 BCa patients revealed that HMGB1 and HMGB2 were overexpressed in BCa tissues compared with normal tissues, and were correlated with tumor clinical stage and pathological grade." (PMID 23426143, 2013). "Similarly, HMGB2 expression was up-regulated in the tumor region from GSE140228 dataset." (PMID 40315321, 2025). "The role of HMGB2 in regulating NK cell function was further supported, suggesting that HMGB2 may be a potential therapeutic target for enhancing NK cell-mediated anti-tumor immunity." (PMID 41280896, 2025). "HMGB2 may regulate the cell cycle to influence tumor progression and metastasis." (PMID 41354099, 2025). "Thus, we speculated that inhibiting HMGB2 contributed to an inflammatory tumor environment by promoting CXCL10 secretion." (PMID 40315321, 2025). "Interestingly, HMGB2 expression has been reported to be correlated with tumor aggressiveness." (PMID 34725363, 2021). "Additionally, IHC results revealed that HMGB2 was highly expressed in NSCLC tumour tissues." (PMID 34651416, 2021). "Therefore, in candidate tumor types, HMGB2, an APA site-targeting gene, may be differentially expressed or regulated in many tumor types, validating the efficacy and accuracy of our prediction." (PMID 32626751, 2020).
tumor (continued). "HMGB2 expression was knocked down in RAW264.7 cells, and the phagocytic activity toward each tumor cell type was assessed using a fluorescence microscopy-based phagocytosis assay." (PMID 40396172, 2025). "Collectively, HMGB2 was highly expressed in the TEX and positively correlated with advanced tumor stage." (PMID 40315321, 2025). "In vivo, HMGB2 promoted HCC growth on two levels, as demonstrated by the subcutaneous tumor differences between immunocompetent and immunodeficient mouse." (PMID 40315321, 2025). "The results demonstrated that HMGB2 silencing markedly enhanced NK cell-mediated cytotoxicity against ESCC cells, as indicated by increased tumor cell killing and elevated cytokine production." (PMID 41280896, 2025). "Mechanistically, HMGB2 impaired the oxidative phosphorylation in CD8+ T cells and inactivated the interferon-γ response in tumor cells, reducing the antitumor effector function." (PMID 40315321, 2025). "Flow cytometry confirmed upregulation of HMGB2 in NK cells from ESCC patients, correlating with advanced tumor stage." (PMID 41280896, 2025). "HMGB2 silencing or knockout enhanced NK cell cytotoxicity, evidenced by increased granzyme B, perforin, IFN-γ, and TNF-α, and higher tumor cell lysis." (PMID 41280896, 2025). "For example, Centromere Protein U (CENPU) enhances glycolysis and proliferation by upregulating High Mobility Group Box 2 (HMGB2), while CD73 is induced under hypoxia to boost glycolytic capacity and promote tumor growth." (PMID 41220952, 2025). "In our study, T1 exhibited the worst degree of differentiation, with the predominant cell type being tumour cells expressing signature markers such as TOP2A and HMGB2." (PMID 40099956, 2025). "Elevated HMGB2 expression demonstrates significant positive correlations with both VEGF upregulation and increased MVD in tumor tissues (p < 0.05)." (PMID 41354099, 2025). "Targeting HMGB2 on both CD8+ T cells and tumor cells contributed to promising treatment strategies for HCC." (PMID 40315321, 2025). "HMGB2, a member of the high-mobility group box (HMG-box) family, has emerged as a critical regulator of tumor progression through its involvement in cell cycle regulation, metabolic reprogramming, and immune evasion mechanisms." (PMID 40396172, 2025). "HMGB2 in POSTN+ fibroblasts is predicted to bind to PLD2, LRP5, MYLK, and CD44 on tumor cells, regulating downstream genes, including BIRC5, CCNA2, CCNB1, CCNB2, CDC20, and MKI67, which are related to the cell cycle." (PMID 38519500, 2024). "Despite these limitations, our study represents a significant contribution to understanding the complex interplay between HMGB2, HCC progression, and the tumor immune microenvironment." (PMID 39247201, 2024). "Two other studies suggested miR-590-3p played an intermediate tumor suppressor role in the LINC0016/miR-590-3p/ROCK and PART1/miR-590-3p/HMGB2." (PMID 37138218, 2023). "Our findings showed a cell-intrinsic role for HMGB2 in the differentiation and stemness of memory and exhausted CD8+ T cells in viral and tumor models." (PMID 37704621, 2023). "HMGB2/3 levels were significantly elevated in both LUAD and LUSC tumor tissues when compared to corresponding normal tissues; data from the Human Protein Atlas followed a similar pattern." (PMID 35923467, 2022). "HMGB2 expression was positively correlated with LINC00184 expression and negatively correlated with miR‐524‐5p expression in NSCLC tumour tissues." (PMID 34651416, 2021). "LINC00184 suppressed tumour growth and proliferation in NSCLC mouse models and directly targeted the miR‐524‐5p/HMGB2 axis." (PMID 34651416, 2021). "The expression levels of HMGB2 in NSCLC tumour and normal tissues were detected via qRT‐PCR; results showed that HMGB2 expression was significantly up‐regulated in tumour tissues compared with that in the normal group (P < 0.0001)." (PMID 34651416, 2021).
tumor (continued). "Two proteins that interact with HMGB2, COMMD1 and MIEN1, are identified in SKOV-3 and tumor tissue libraries, which cross-validate these results." (PMID 32867128, 2020). "The genes, ZWINT, E2F1, HMGB2, KPNA2, and CKS2, were expressed at low or moderate levels in non-tumor tissues." (PMID 31695969, 2019). "Libraries constructed from the PCa cell line, PC-3, and from patients’ PCa primary tumor have been screened by the yeast 2-hybrid approach (Y2H) using HMGB1 and HMGB2 baits." (PMID 31694235, 2019). "Also, given the role CpG island hypermethylation on gene silencing and the numerous reports of HMGB overexpression in tumor tissue, we might expect to see the opposite results (i.e., CpG island hypomethlation of HMGB2) if in fact, CTCs were driving force behind the methylation signals detected here." (PMID 24479488, 2014). "Similarly, HMGB2 knockdown impairs GBM cell viability and invasiveness in vitro, reduces tumor volume in vivo, and enhances sensitivity to temozolomide, positioning it as a viable target for combinatorial therapy." (PMID 40852729, 2025). "Although high-mobility group box 2 (HMGB2) has been reported to be crucial to HCC prognosis, its role in the tumor microenvironment remains unclear." (PMID 40315321, 2025). "Furthermore, our study did not evaluate the potential contribution of other immune cell populations in the tumor microenvironment, such as T cells, B cells, or myeloid-derived suppressor cells, which may interact with NK cells and influence the immunological role of HMGB2." (PMID 41280896, 2025). "HMGB2 is highly expressed in multiple solid tumors and is an independent risk factor for poor prognosis of HCC, but its mechanism for promoting tumor progression has not been thoroughly investigated." (PMID 40315321, 2025). "Flow cytometry further verified that HMGB2 expression was markedly elevated in T cells, B cells, and particularly in the CD3-CD56+ NK cell subset of ESCC patients, where its expression level was positively correlated with tumor stage." (PMID 41280896, 2025). "Together, tannic acid served as the specificity inhibitor for HMGB2 in vivo, which failed to control tumor growth after Hmgb2 disruption in tumor cell and CD8+ T cell." (PMID 40315321, 2025). "This may serve as a crucial insight for future understanding of how HMGB2 promotes immunosuppression in the local immune microenvironment of HCC, thereby facilitating tumor invasion, metastasis, or resistance to immunotherapy." (PMID 39247201, 2024). "HMGB2 expression was reduced or absent in multinucleated giant tumor cells in both primary and recurrent tumors." (PMID 38672598, 2024). "Of note, HMG family proteins such as HMGB1, HMGB2 and HMGB3 are elevated in human tumor cell NEPs in contrast to S100a4 in mice suggesting that NEP signaling through the RAGE pathway may be conserved between mice and humans." (PMID 36973439, 2023). "HMGB2, as a member of high-mobility group box(HMGB) proteins family, is involved in DNA replication, repair, transcription, differentiation, proliferation, cell signaling, inflammation, tumor migration, and cellular senescence." (PMID 37903974, 2023). "The overexpression of HMGB/HMGB2 was correlated with both the clinical stage and pathological grade of the tumor, and HMGB1 and HMGB2 may be involved in BCa development and progression." (PMID 23426143, 2013). "In conclusion, our study finds a previously unknown T cell exhaustion–associated target at the single-cell level and reveals mechanisms by which HMGB2 impairs mitochondrial OXPHOS in CD8+ T cells and inhibits IFN-γ response in tumor cells, thus inducing immune evasion of HCC." (PMID 40315321, 2025). "Our aim was to describe HMGB2 expression in tumor cells and in the non-neoplastic adjacent brain tissue, its subcellular location and relationship with histopathological hallmarks of tumor grade and IDH status." (PMID 38672598, 2024).
tumor (continued). "Additionally, our study demonstrated that HMGB2 was associated with worse OS, DFS, and PFS in patients, HMGB2 expression was significantly higher in patients with advanced tumor progression or non-response to antitumor therapy." (PMID 39247201, 2024). "Finally, based on our findings, due to the high specificity of HMGB2 expression in tumor cells, but not in normal brain cells, the role of HMGB2 expression as prognostic and/or predictive biomarker is promising." (PMID 38672598, 2024). "Importantly, in the areas representative of the infiltrative edge, HMGB2 expression was sometimes cytoplasmic in tumor cells, while being mostly absent from non-neoplastic oligodendrocytes, astrocytes, and neurons, both in GBMs and in grades 2 and 3 and A4 IDHmut." (PMID 38672598, 2024). "To evaluate the influence of HMGB2 on effector function, we conducted flow cytometry and electron microscopy analysis on NC and Hmgb2-cKO OT-I CD8+ cells with or without tumor stimulation by Hepa1-6–ovalbumin (OVA) cells." (PMID 40315321, 2025). "After the detection of 3 HMGB2-derived circRNAs in 8 pairs of NSCLC tissues and matched normal tissues, circHMGB2 (hsa_circ_0071452) was found to be highly expressed in tumor tissues, and high circHMGB2 expression was identified as an indicator of poor prognosis in NSCLC patients." (PMID 35525959, 2022).